PRNP (prion protein (Kanno blood group))
Diseases named in the same sentence as PRNP in open-access papers (continued):
Sharing a sentence is not in itself a finding about the gene and the disease.
scrapie (303 papers, 2005 to 2026). A fatal disease of the nervous system in sheep and goats, characterized by pruritus, debility, and locomotor incoordination. "Genetic selection for PRNP alleles associated with resistance to classical scrapie, particularly K222 and S127, has been proposed as a control strategy, but their effect on caprine BSE is unclear." (PMID 42063174, 2026). "Further studies are needed to investigate the role that PRNP polymorphisms play in the disease progression of WTD scrapie in white-tailed deer." (PMID 39043428, 2024). "The plan involves genotyping of PRNP at positions corresponding to codons 146 and 222 to assess resistance or susceptibility to classical scrapie." (PMID 39107851, 2024). "The susceptibility of small ruminants (i.e. goat and sheep) to scrapie are affected by the genetic variation of the PRNP gene." (PMID 38355406, 2024). "In sheep, linkage disequilibrium (LD) analysis revealed a significant linkage between the G allele of codon 26 of the ovine PRND gene and the ARR allele of the ovine PRNP gene, known to confer genetic resistance to scrapie." (PMID 38952802, 2024). "The PRNP gene, which encodes the PrPC protein, plays a crucial role in determining susceptibility and resistance to scrapie." (PMID 39107851, 2024). "The prion protein-encoding gene (PRNP) plays a crucial role in determining susceptibility and resistance to scrapie." (PMID 39107851, 2024). "Herein, we examined the genotype and allele frequencies of PRNP polymorphisms in 126 Nigerian sheep and compared the sampled population with previous studies on scrapie-affected animals in different breeds of sheep." (PMID 36892181, 2023). "Scrapie is a fatal, neurodegenerative disease that affects sheep and goats, and genetic susceptibility to scrapie in sheep is associated with polymorphisms in the prion protein (PRNP) gene." (PMID 37888549, 2023). "Three polymorphisms at codons 136, 154, and 171 have been linked to classical scrapie susceptibility, although many variants of PRNP have been reported." (PMID 36892181, 2023). "Because of the limited studies on scrapie in the Fertile Crescent region and the importance of this region, the sheep reared in these places should be screened for PRNP variants and evaluated for the risk of scrapie." (PMID 37888549, 2023). "According to many studies on scrapie-affected sheep, resistance or susceptibility to scrapie is strongly associated with polymorphisms of codons 136, 154 and 171 of the PRNP." (PMID 37888549, 2023). "In this study, we aimed to identify PRNP polymorphism in nucleotide sequences of 126 Nigerian sheep by comparing them with public available studies on scrapie-affected sheep." (PMID 36892181, 2023). "The aim of this study is the identification of polymorphisms and possible new variants in PRNP and the evaluation of genetic resistance or susceptibility to scrapie in Awassi sheep reared in Türkiye, the Palestinian Authority, and Saudi Arabia." (PMID 37888549, 2023). "Several goat PRNP polymorphisms have been reported, and some genotypes have been associated with reduced susceptibility to classical scrapie." (PMID 37773068, 2023). "The susceptibility of animals to scrapie is predominantly controlled by polymorphism in the PRNP gene." (PMID 36892181, 2023). "Polymorphism of the prion protein gene (PRNP) gene determines an animal’s susceptibility to scrapie." (PMID 36892181, 2023). "Our results regarding PRNP polymorphisms in Awassi sheep will help the scrapie breeding programs aiming to increase the prevalence of resistant genotypes in sheep populations and thereby reduce the risk of scrapie." (PMID 37888549, 2023). "In European sheep breeds, PRNP polymorphisms have been studied and predicted to be associated with resistance or susceptibility to scrapie through case studies." (PMID 37888549, 2023).
scrapie (continued). "Previous studies identified three polymorphic codons (136 A (Alanine)/V (Valine), 154 R (Arginine)/H (Histidine), and 171 Q (Glutamine)/R/H) in sheep PRNP that are related to scrapie resistance/susceptibility status." (PMID 33806658, 2021). "Studies often report the genotype of sheep as a sequence of three one-letter amino acid codes at codons 136, 154, and 171 of the PRNP gene that are of interest due to their influence on susceptibility to scrapie." (PMID 34960722, 2021). "Many European studies showed that allele variation and polymorphisms of the PRNP gene can determine the susceptibility or resistance to classical scrapie in goats, but only a few of them have been proven to be associated with resistance." (PMID 33525718, 2021). "Only 2 of 8 inoculated lambs developed lesions compatible with a prion disease, and they expressed different PRNP genotypes at codons 136, 154 and 171, which are known to determine sheep susceptibility to scrapie." (PMID 34488900, 2021). "In goats, as in sheep, genotypes of the prion protein gene (PRNP) can influence animals’ susceptibility to scrapie." (PMID 33525718, 2021). "There is polymorphic variation in the sheep PRNP at amino acid positions 136, 154, and 171 that affects susceptibility to scrapie, and the VRQ, ARQ, and ARR genotypes have the greatest effect in this regard." (PMID 34413769, 2021). "Polymorphisms of the prion protein gene (PRNP) strongly modulate scrapie resistance and incubation period in goats." (PMID 34280230, 2021). "Further research on the PRNP codon 222 indicated all goats that were diagnosed with classical scrapie were almost entirely composed of the QQ222 variant." (PMID 34280230, 2021). "There are a number of polymorphisms in the PRNP gene of sheep that affect susceptibility and incubation time of different strains of scrapie." (PMID 34960722, 2021). "There is a clear influence of the PRNP genotype for codons 136, 154, and 171 regarding the susceptibility of classical scrapie." (PMID 33806658, 2021). "In goats, codons Ile142Met, His143Arg, Asn146Ser, Arg211Gln, and Gln222Lys of the caprine PRNP gene were linked to the protection against scrapie development." (PMID 32532135, 2020). "In humans, variation in the number of octarepeat units (PHGGGWGQ) in the PRNP gene affects the frequency of prion disease, and polymorphisms in this repeat also affect progression of scrapie in sheep and goats." (PMID 32715865, 2020). "Nevertheless, two other PRNP polymorphisms, S146 and K222, have been identified to confer strong resistance towards scrapie in goats, even in heterozygous animals." (PMID 31924264, 2020). "As animal models we used sheep naturally infected with classical scrapie and transgenic Tg338 mice that overexpress the highly susceptible variant of the ovine PRNP gene." (PMID 32370154, 2020). "In sheep, scrapie risk-groups have been defined according to the composition of haplotypes at codons 136, 154, and 171 of ovine PRNP." (PMID 32532135, 2020). "In goats, alleles 143R, 146N, 154R, 211R and 222Q in the relevant codons of the PRNP gene have been associated with scrapie susceptibility in Greece, France and Cyprus10–13." (PMID 31649311, 2019). "Although breeding programs selecting for less susceptible PRNP genotypes can be effective in reducing scrapie prevalence in flocks, our data regarding the impact of deer PRNP genotypes need to be interpreted with caution." (PMID 30717795, 2019). "Identification of scrapie or BSE status in goats can be complicated due to the existence of several polymorphisms in the PRNP coding sequence which can delay the incubation period and PrPSc accumulation." (PMID 30992522, 2019). "Polymorphisms at PRNP gene locus have been associated with resistance against classical scrapie in goats." (PMID 29879210, 2018). "Codons 136, 154 and 171 in the ovine PRNP gene are well known to be associated with the susceptibility to scrapie in sheep." (PMID 30359416, 2018).
scrapie (continued). "In a previous study, it was demonstrated that a strong genetic linkage existed in scrapie-associated SNPs between the PRNP and PRND genes in sheep." (PMID 30359416, 2018). "Because goats are another major host of scrapie, we searched for such genetic linkage in the scrapie-associated SNPs among the PRNP, PRND and PRNT genes in Korean native black goats." (PMID 30359416, 2018). "The notion is that success of such programs is subject to in-depth knowledge of the frequency and distribution of PRNP polymorphisms conferring resistance to classical scrapie." (PMID 29879210, 2018). "In sheep, susceptibility to classical scrapie is modulated by the PRNP gene which encodes PrPC protein." (PMID 29879210, 2018). "For goats, field and experimental studies have provided evidence for several amino acid polymorphisms that are associated with resistance to scrapie, but only limited data are available concerning the susceptibility of caprine PRNP genotypes to BSE." (PMID 28927447, 2017). "In sheep, classical forms of scrapie have been eradicated almost completely in several countries by breeding programs using a prion protein (PrP) gene (PRNP) amino acid polymorphism." (PMID 28927447, 2017). "Susceptibility of goats to scrapie is influenced by polymorphisms of the prion protein gene (PRNP) of the host." (PMID 27716411, 2016). "As already described for sheep, the susceptibility of goats for scrapie is highly influenced by polymorphisms of the prion protein gene (PRNP)." (PMID 27716411, 2016). "In this study, we report that rabbits engineered to express transgenetically the V136R154Q171 ovine PRNP allele develop a TSE syndrome upon experimental inoculation with scrapie." (PMID 26248157, 2015). "In sheep, different PRNP alleles tightly modulate the incidence and pathogenesis of classical scrapie." (PMID 26248157, 2015). "The other interesting difference between the BSE and scrapie inocula is the response of sheep that carry the ARR PRNP allele as homozygous or heterozygous genotypes." (PMID 26587837, 2015). "In separate experiments, milk obtained from scrapie infected sheep and goats was used to experimentally infect naïve new-born lambs of susceptible prion protein (PRNP) genotypes with high efficiency." (PMID 26511838, 2015). "Recipient lambs were homozygous for the scrapie-susceptible ovine PRNP haplotype, which codes for valine at position 136 (i.e. VV136)." (PMID 25888622, 2015). "The purpose of this study was to compare the survival time and PrPSc tissue distribution in sheep with highly resistant and highly susceptible PRNP genotypes after intracranial inoculation of the agent of scrapie." (PMID 25233232, 2014). "Further, based on the results presented here and on other studies on Greek goat PRNP alleles and their association with scrapie, we suggest the design of a goat-scrapie resistance program targeting the Q211, S146 and K222 alleles." (PMID 24717012, 2014). "The prion protein gene (PRNP) profoundly influences the susceptibility of sheep to the scrapie agent and the tissue levels and distribution of PrPSc in affected sheep." (PMID 25233232, 2014). "New Zealand Cheviot sheep, homozygous for the VRQ genotype of the PRNP gene are most susceptible with an incubation period of 193 days with SSBP/1 scrapie." (PMID 25183238, 2014). "The purpose of this study was to compare the survival time and PrPSc tissue distribution in sheep with highly resistant and highly susceptible PRNP genotypes after intracranial inoculation of the agent of classical scrapie." (PMID 25233232, 2014). "The ovine PRNP genotype determines susceptibility to scrapie and is one of the best studied factors known to affect the spread of the scrapie agent." (PMID 24828439, 2014). "The present study investigates the potential use of the scrapie-protective Q211 S146 and K222 caprine PRNP alleles as targets for selective breeding in Greek goats." (PMID 24717012, 2014).
scrapie (continued). "The susceptibility of sheep to scrapie is greatly influenced by host prion protein gene (PRNP) alleles." (PMID 25233232, 2014). "While the precise number scrapie strains in sheep and goats remains uncertain, the description of at least 24 additional major sheep PRNP polymorphisms, and combinations thereof, is likely to have a significant influence on strain diversity." (PMID 24204258, 2013). "European studies have now suggested that several polymorphisms can modulate scrapie susceptibility in goats: in particular, PRNP variant K222 has been associated with resistance in case-control studies in Italy, France and Greece." (PMID 22296670, 2012). "Brain tissue from a sheep homozygous for the PRNP ARQ allele was used as a reference ovine scrapie case." (PMID 22472560, 2012). "Our study confirms that variant K222 of the goat PRNP gene can be a genetic target to select for in the frame of breeding programs for the control and eradication of classical scrapie in goats." (PMID 22296670, 2012). "Susceptibility of sheep to scrapie, a transmissible spongiform encephalopathy of small ruminants, is strongly influenced by polymorphisms of the prion protein gene (PRNP)." (PMID 22296670, 2012). "Although an infectious disease, the susceptibility of sheep to scrapie is strongly influenced by polymorphisms of the prion protein gene (PRNP)." (PMID 22296670, 2012). "Our study shows that PRNP gene mutation K222 is strongly associated with resistance to classical scrapie in experimentally challenged goats, confirming the results previously obtained in field studies." (PMID 22296670, 2012). "In sheep polymorphisms of the prion gene (PRNP) at the codons 136, 154 and 171 strongly influence the susceptibility to scrapie and bovine spongiform encephalopathy (BSE) infections." (PMID 21324112, 2011). "In summary, the here reported in vitro conversion studies support the association of specific ovine and caprine PRNP polymorphisms with a reduced classical scrapie susceptibilities in vivo." (PMID 21324112, 2011). "Sheep carrying the PRNP polymorphisms valine (V) or alanine (A) at codon 136 (136V and 136A) are highly susceptible to classical scrapie, while the exchange of arginine (R) to histidine at codon 154 (154H) is linked to low scrapie susceptibility." (PMID 21324112, 2011). "The four scrapie infected breeding goats were homozygous for the wild type (wt) PRNP haplotype encoding 240 S (n = 1), homozygous for the alternative central haplotype encoding 240P (n = 2), or heterozygous for these two haplotypes (n = 1)." (PMID 21284878, 2011). "A reduced susceptibility to natural scrapie has also been reported for goats carrying arginine (R) at codon 143 (143R) and histidine (H) at codon 154 (154H) in the PRNP gene as well as for goats with glutamine (Q) at codon 211 (211Q)." (PMID 21324112, 2011). "Though ovine PRNP polymorphism has been abundantly linked to the scrapie risk, a few studies have been carried out for the analysis of caprine PRNP gene in this regard." (PMID 22044871, 2011). "Other PRNP codon variants associated with disease resistance include those for atypical scrapie and experimental BSE challenge in sheep." (PMID 20433741, 2010). "Genetic predisposition to scrapie in sheep is associated with several variations in the peptide sequence of the prion protein gene (PRNP)." (PMID 20433741, 2010). "Increased resistance to classical scrapie is associated with a prion protein gene (PRNP) haplotype allele encoding alanine (A), arginine (R), and R at codon positions 136, 154, and 171, respectively (i.e., ARR)." (PMID 20433741, 2010). "PRNP mutations associated with susceptibility to atypical scrapie include a L141F variant and a rare octapeptide repeat insertion." (PMID 20433741, 2010). "First reported in Norwegian sheep in 2003 and referred to as Nor98, atypical scrapie appears to be a single, unique scrapie strain infecting sheep with PRNP genotypes usually associated with resistance to classical scrapie." (PMID 18769716, 2008).
scrapie (continued). "Recent molecular studies have identified promising genetic markers associated with disease resistance, notably polymorphisms in the MHC complex (particularly DRB1 and DQB1 loci) conferring protection against parasitic infections and the PRNP gene variants influencing scrapie susceptibility." (PMID 40933525, 2025). "Additionally, single nucleotide polymorphisms (SNPs) at codons 102, 127, 142, 143, 146, 154, 211, and 222 in the caprine PRNP gene are key genetic markers used to predict susceptibility to scrapie in goats, with specific genotypes providing greater resistance." (PMID 39682402, 2024). "Consequently, the major homozygote genotype of caprine PRND SNPs is genetically associated with the caprine PRNP HH genotype, which is related to scrapie progression." (PMID 38952802, 2024). "PRNP genes are highly polymorphic in goats, and the distributions of genotype and haplotype frequencies at codons 139, 146, and 154 were highly associated with vulnerability to scrapie in goats." (PMID 38355406, 2024). "Additionally, SNPs c.28T>C, c.151A>G, and c.385G>C in the caprine PRND gene are strongly linked with the SNP c.428A>G (H143R) of the PRNP gene, which is associated with scrapie progression." (PMID 39682402, 2024). "The polymorphism of the PRNP gene at codons 136 [Alanine (A) or Valine (V)], 154 [arginine (A) or histidine (H)], and 171 [R, H or glutamine (G)] are highly related to vulnerability or resistance to scrapie in sheep." (PMID 36892181, 2023). "The H154 allele is of particular interest because it is present in both the ovine and caprine PRNP gene and has been correlated with high susceptibility to the atypical scrapie in sheep, suggesting that it could be a risk factor for atypical scrapie in goats." (PMID 34280230, 2021). "In sheep, the proteolytic processing of PrPC in the brain depends on the PRNP genotype, such that the relative amount of the C1 fragment is increased and that of the C2 fragment is decreased in PRNP genotypes associated with resistance to classical scrapie." (PMID 34147084, 2021). "Some PRNP polymorphisms have been associated with different levels of resistance to scrapie." (PMID 34073078, 2021). "In the present study, we determined the PRNP polymorphisms of native and crossed goat populations, which are the only two goat populations raised in the Southeast of Tunisia in order to evaluate the presence of polymorphisms associated with scrapie resistance." (PMID 34073078, 2021). "As already done in sheep, single nucleotide polymorphisms (SNPs) of PRNP in goats could represent an opportunity to classify caprine genotypes in those susceptible or resistant to scrapie." (PMID 33525718, 2021). "In particular, at least 50 PRNP polymorphisms have been described in goat breeds, but their involvement in the modulation of the incubation times and in susceptibility to classical scrapie is less defined than in sheep." (PMID 33525718, 2021). "Vázquez-Miranda and Zink pointed out that a single mutation in the PRNP gene in white-tailed deer could yield a genotype similar to the one in sheep that provides resistance to scrapie." (PMID 32715865, 2020). "Thus, it would be of great interest to investigate scrapie-resistance in PRNP+/Ter animals upon oral inoculation, since PRNP-expression in gut-associated lymphatic tissue is obligate for transmission of scrapie under natural conditions." (PMID 31924264, 2020). "In addition, the scrapie susceptibility-related PRNP SNPs showed a strong LD with PRND and PRNT SNPs." (PMID 31649311, 2019). "Polymorphisms of the prion protein gene (PRNP) sequences may influence scrapie susceptibility in sheep and goats through modified protein conformation." (PMID 31053138, 2019). "The analysis of the prion protein gene PRNP in 229 goats belonging to three of the main Ethiopian native goat breeds showed a remarkably high frequency (> 34.6%) of p.(Asn146Ser) in these breeds, a variant involved in scrapie resistance in Cyprus." (PMID 31053138, 2019).